KAT6A (lysine acetyltransferase 6A)
Diseases named in the same sentence as KAT6A in open-access papers (continued):
Sharing a sentence is not in itself a finding about the gene and the disease.
tumor (32 papers, 2014 to 2025). "KAT6A has been implicated to either promote or inhibit senescence, important for tumor formation and growth." (PMID 31888644, 2019). "KAT5 and KAT6A were associated with prognosis and tumor mutation burden in KIRC." (PMID 37365518, 2023). "Application of CIP approaches to inhibit or degrade KAT6A is thought to achieve better tumor‐specific targeting of KAT6A and broaden the therapeutic window for KAT6A suppression." (PMID 41357671, 2025). "The KAT6A knockout group exhibited slower tumor growth and longer survival after PARPi treatment than the other groups." (PMID 38973255, 2024). "The inhibition of histone acetyltransferases KAT6A/B contributes to senescence and regulates tumor growth." (PMID 35432536, 2022). "Consistent with previous observations, KD of KAT6A inhibited tumor growth, lung metastasis, and prolonged survival of orthotopic 4T1 tumor xenograft‐bearing animals." (PMID 34392614, 2021). "Repression of KAT6A resulted in attenuated cell proliferation, invasion and metastasis in vitro and xenograft tumor growth." (PMID 33995658, 2021). "The first series included 11 KAT6B::KANSL1 and 2 KAT6A::KANSL1 tumours." (PMID 39392508, 2024). "Notably, while some of the targets revealed by our analysis (such as IGF1R, HGF, and KAT6A), are well-characterized drivers of tumorigenesis, others are known tumor suppressors e.g., PTEN, EP300." (PMID 35347083, 2022). "Similarly, heterozygous loss of the gene encoding the histone acetyltransferase MOZ (Kat6a) slowed down the proliferation of malignant B-cells, and pharmacological inhibition of MOZ reduced E2F2 transcription, stopping tumor growth in vivo." (PMID 36611833, 2022). "KAT6A directly binds to and acetylates SMAD3 at K20 and K117, which promotes SMAD3 association with oncogenic chromatin modifier TRIM24 and disrupts its interaction with tumor suppressor TRIM33." (PMID 34392614, 2021). "Additionally, functional experiments uncovered an oncogenic role of KAT6A, which acts as a key factor that links the platinum response to tumor spread through the stabilization of β-catenin protein." (PMID 33995658, 2021). "In addition, AKT2 (p = 0.002) and KAT6A (p = 0.015) amplifications were more frequent in tumor samples from younger patients (<60), and CEBPA (p = 0.028) and MYC (p = 0.023) amplifications were more common with advanced (stage III and IV) disease stage." (PMID 32877461, 2020). "KAT6A was also hypothesized to suppress tumor when severe DNA damage happened." (PMID 31888644, 2019). "These KAT6 inhibitors were shown to exhibit effective inhibition against both KAT6A and KAT6B, induce cellular senescence, and impede tumor growth in models of MYC‐driven lymphoma and AML." (PMID 41357671, 2025). "In other types of tumors, KAT6A and KAT6B have been reported to mediate tumor proliferation and malignant progression through the PI3K/AKT signaling pathway, while inhibition of KAT6A and KAT6B results in decreased phosphorylation of PI3K and AKT." (PMID 41357671, 2025). "Our study cohort consisted of 16 tumours harboring a KAT6B/A::KANSL1 gene fusion (KAT6B::KANSL1, n = 15; KAT6A::KANSL1, n = 1)." (PMID 39392508, 2024).
tumor (continued). "A small‐molecular inhibitor targeting KAT6A increases the efficacy of anti‐PD‐L1 therapy by inhibiting TNBC metastasis and significantly prolongs the survival for tumor xenograft‐bearing animals." (PMID 34392614, 2021). "Moreover, preclinical data from cell lines and animal models indicate that approaches targeting subunits of KAT6A and KAT6B can effectively inhibit tumor growth via mechanisms including cell cycle arrest and cell senescence." (PMID 41357671, 2025). "Importantly, abnormal regulation of KAT6A and KAT6B has been shown to serve as tumor drivers or suppressors, which places a critical impact on the formation, progression, and drug resistance of cancerous disorders." (PMID 41357671, 2025). "Finally, we assessed the influence of the disruption of KAT6A and PARP1 interaction on tumor cell survival in vivo." (PMID 38973255, 2024). "Knockdown (KD) of KAT6A with two different shRNAs significantly decreased cell proliferation in MDA‐MB‐231 and BT‐549 cells and orthotopic xenograft tumor growth." (PMID 34392614, 2021). "TNBC tumors with distant metastasis showed a remarkably higher KAT6A expression than those without tumor metastasis." (PMID 34392614, 2021). "Moreover, KAT6A KD decreased cell invasion and migration in MDA‐MB‐231 and BT‐549 cells and tumor metastasis to the lungs." (PMID 34392614, 2021). "Amplification of oncogenes KAT6A and NSD3 (previously known as WHSC1L1) in this region may be involved in driving tumor cell growth and carcinogenesis." (PMID 28957377, 2017). "Inhibition of KAT6A and KAT6B could induce senescence and arrest tumor growth." (PMID 37365518, 2023). "Ectopic expression of the SMAD3 2KQ mutant, but not WT, not only rescued KAT6A KD‐inhibited tumor growth, lung metastasis, markedly reduced the animal survival, but also promoted MDSCs recruitment to lung tissues and primary tumor, CD4+/CD8+ T cells depletion in metastatic lung tissues." (PMID 34392614, 2021). "Densitometry analysis showed that KAT6A, KAT6B and KAT7 significantly decreased in KIRC tumor tissues, but KAT5 in KIRC tumor tissues decreased to some extent, but the change was not significant." (PMID 37365518, 2023).
neurodevelopmental disorder (11 papers, 2017 to 2026). A behavioral and cognitive disorder with onset during the developmental period that involves impaired or aberrant development of intellectual, motor, or social functions. "We demonstrate that FBRSL1 associates with the transcription factor Yin Yang 1 (YY1) and binds upstream of Bromodomain And PHD Finger containing 1 (BRPF1) and Lysine Acetyltransferase 6 A (KAT6A), two epigenetic regulators involved in embryonic development and linked to neurodevelopmental disorders." (PMID 40658195, 2025). "Interestingly, four of these LoF variants disrupted genes previously implicated in neurodevelopmental disorders: KAT6A (c.1599-56_1621del in proband 10), SETBP1 (c.1781del, p.P594Lfs*36 in proband 13), TNRC6B (c.2040G>A, p.W680* in proband 15) and ZFHX4 (c.3646-1G>A in proband 14)." (PMID 29463886, 2019). "While K604R possesses an arginine substitution of K604, the sole autoacetylation site required for the acyltransferase activity of KAT6A, the other mutants of KAT6A and its HAT domain are clinical variants identified in patients with a neurodevelopmental disorder." (PMID 41221126, 2025). "A significant number of these genes (CHD3, SETD1A, KAT6A, SETBP1, TNRC6B, ZFHX4, ARID1A and TRIO) have been associated with neurodevelopmental disorders with or without speech problems." (PMID 29463886, 2019).
genetic disorder (7 papers, 2015 to 2025). "For variants found within genes that have recently been linked to a genetic disorder and for variants with uncertain significance, such as ones located within KAT6A and PIEZO2, further work was carried out to assess their pathogenicity." (PMID 34324503, 2021). "KAT6A syndrome (Arboleda–Tham syndrome; ARTHS; MIM#616268) is a genetic disorder first characterized in 2015." (PMID 34439586, 2021).
hematologic malignancies (3 papers, 2015 to 2025). "In the majority of cases of solid tumors and hematologic malignancies, KAT6A and KAT6B function as oncogenes." (PMID 41357671, 2025). "In addition to hematologic malignancies, recurrent amplifications of KAT6A have been reported in various solid tumors, including breast cancer, ovarian cancer, uterine cervix cancer, lung adenocarcinoma, colon and rectal cancer." (PMID 36077605, 2022).
KAT6A also shares sentences with these, for which no sentence is quoted: microcephaly (4 papers); myelodysplastic syndrome (3); apraxia (2); autism (2); breast tumor (2); epilepsy (2); food allergies (2); monocytic leukemia (2); myocardial infarction (2); ovarian tumor (2); acute leukemia (1); acute lymphoblastic leukemia (1); acute mixed-lineage leukemia (1); Acute Monoblastic Leukemia (1); acute promyelocytic leukemia (1); allergies (1); amyotrophic lateral sclerosis (1); Ascites (1); autism spectrum disorder (1); brain cancer (1); cardiac arrhythmias (1); cervical cancer (1); Coffin-Siris syndrome (1); Cognitive impairment (1); congenital heart defects (1); conotruncal heart defects (1); desmoid-type fibromatosis (1); Down syndrome (1); endometriosis (1); endometrium cancer (1).
A further 23 diseases each share a sentence with KAT6A in 1 paper.